AR (androgen receptor)
Diseases named in the same sentence as AR in open-access papers (continued):
Sharing a sentence is not in itself a finding about the gene and the disease.
prostate carcinoma (continued). "This review highlights the metabolic crosstalk between IF and AR signaling and emphasizes the need for future clinical studies incorporating biomarker-guided approaches and body composition monitoring to fully exploit this intersection for improved therapeutic outcomes in prostate cancer." (PMID 41898513, 2026). "This cross-talk may be particularly relevant in hormone-dependent cancers such as breast and prostate cancers, in which inhibition of the dominant hormone receptor (i.e., AR in prostate cancer) can lead to alternative hormone receptors supporting tumor cell growth by hijacking the signaling cascade." (PMID 41486951, 2026). "In addition, AR mutation is found not just in cases with CAIS but also in prostate cancer and Kennedy’s syndrome." (PMID 41163677, 2025). "Moreover, it remains to be studied whether hypoxia-driven upregulation of CNPY2 (via HIF-1α) additionally modifies any of these post-translational events, creating a feedforward loop that further stabilizes AR in castration-resistant prostate cancer." (PMID 40001982, 2025). "Subsequently, we induced hypospadias in rats by gestational exposure using the prostate cancer drug and potent AR antagonist flutamide as model chemical, with the aim to investigate how anti-androgenic EDCs may impact penis development by affecting both AR and ER signaling." (PMID 41019341, 2025). "Whether the AR-mediated cellular growth seen in prostate cancer cells as well as other dysregulated cellular functions such as PI3K/AKT pathway activity and DNA repair dysfunction render prostate cancers susceptible to CDK4/6 inhibition is an open question." (PMID 40075623, 2025). "Meanwhile, PI3K signal transduction interacts with Wnt, Mitogen-Activated Protein Kinase (MAPK), and AR signaling cascades, synergistically driving prostate cancer growth and therapy resistance, indicating that pathway inhibitors hold broad application potential in prostate cancer." (PMID 41227351, 2025). "To address this, and the fact that multiple HSPs and HSF1 have been implicated in AR signaling, we explored the clinical relevance of the GO cellular response to heat gene expression signature (which includes multiple HSPs and HSF1) in advanced prostate cancer." (PMID 39787247, 2025). "Several subtypes of androgen indifferent prostate cancer have been described in the literature, most notably, neuroendocrine (NE) prostate cancer, although phenotypes that lack NE features but also lack or are low in AR expressed genes have also been described." (PMID 40002188, 2025). "Furthermore, studies suggest that DPP4 may act as a tumor suppressor gene in the AR pathway, and its inhibition could potentially accelerate prostate cancer progression, particularly after androgen deprivation therapy." (PMID 40766751, 2025). "Consequently, the degradation of AR induced by OC could impair homologous recombination repair mechanisms, thereby sensitizing prostate cancer cells to the effects of PARP inhibitors such as olaparib." (PMID 40564985, 2025). "A recently developed androgen receptor (AR) antagonist, psalutamide, significantly inhibited proliferation and migration, induced cysteine protease‐dependent apoptosis, and decreased lipid droplet levels in prostate cancer (PCa) cells by modulating the levels of ACL, ACC, FASN, and SREBP1." (PMID 40145543, 2025). "Moreover, immunohistochemical analysis ofex vivo-irradiated, patient-derived PCa tissues from patients with newly diagnosed high-Gleason score prostate cancer undergoing prostatectomy further demonstrated that radiation-induced autophagy supports the survival of high-grade AR-positive tumor cells." (PMID 41573861, 2025). "However, docetaxel may also benefit patients with prostate cancer through androgen receptor signaling pathways and the inhibition of nuclear translocation." (PMID 40896445, 2025).
prostate carcinoma (continued). "Additionally, variations in the CAG repeat number in the first exon of the AR gene may also impact AR activity, with shorter CAG repeats being associated with an increased risk of prostate cancer." (PMID 40008000, 2025). "NSCLC, for instance, frequently involves KRAS mutations and EGFR pathway alterations, which may interact differently with statin-induced modulation of signalling pathways compared to prostate cancer, where androgen receptor signalling and lipid metabolism are more prominent." (PMID 41163198, 2025). "Indeed, the majority of prostate cancers are driven by the alterations in AR-signaling." (PMID 38383885, 2025). "Finally, CDK1 could be implicated in the progression of specific cancer as observed in prostate carcinomas where it phosphorylates Androgen Receptor (AR), which results in decreased transactivation upon androgen stimuli." (PMID 39800748, 2025). "Therefore, it can be concluded that AR activation in prostate cancer cells may maintain YAP protein stability and activity by reducing Ser-127 phosphorylation levels." (PMID 39963114, 2025). "However, prostate cancer exhibits a unique dependence on AR and tumor stemness, which may enhance the role of AURKA in promoting genomic instability and maintaining tumor invasiveness after AR deprivation." (PMID 40718709, 2025). "Furthermore, AR plays a pivotal role in the development of prostate cancer." (PMID 39963114, 2025). "Additionally, TQB3720 activates ferroptosis via the AR/GPX4 pathway in prostate cancer cells." (PMID 39935430, 2025). "Overall, emerging AR-targeted drugs may hold potential in addressing resistance, yet more robust clinical evidence is required to substantiate their effectiveness and determine their optimal use in prostate cancer therapy." (PMID 41079787, 2025). "Therefore, clarifying the AR signaling mechanism is crucial for the treatment of prostate cancer." (PMID 40503765, 2025). "Additionally, by integrating multi-omics data, researchers can uncover how prostate cancer cells develop resistance to AR-targeted therapies by activating alternative pathways such as PI3K/Akt, providing crucial insights for designing more effective combination therapies." (PMID 40008000, 2025). "In prostate cancer (PC), resistance to systemic therapies such as the androgen receptor pathway inhibitor (ARPI) enzalutamide is associated with a host of well-documented androgen receptor (AR) alterations, including amplification, mutation, and alternative splicing." (PMID 40303463, 2025). "In human prostate cancer‐derived cells, it may take more than 2 days for AR re‐expression." (PMID 40013333, 2025). "Indeed, we were able to detect AR-V567es in one out of more than 200 clinical specimen only, which is in stark contrast to studies demonstrating appearance of AR-V567es in up to 70% of prostate cancer patients." (PMID 40859365, 2025). "Furthermore, androgen induces the association of AR with the DTX3L-PARP9 heterodimer, where PARP9, using its macrodomains (MD1 and MD2), binds to the ADP-ribose moieties on AR deposited by PARP7, thus modulating AR transcriptional activity both positively and negatively in prostate cancer cells." (PMID 40128585, 2025). "Additionally, we investigated whether there is a regulatory relationship between this transcriptional regulatory circuit and AR, the driver gene of prostate cancer." (PMID 40470696, 2025). "Additionally, small-molecule compounds targeting NONO can inhibit the expression of androgen receptor and its splice variants in prostate cancer by covalently binding to the C145 site of NONO, thereby inhibiting cancer cell proliferation." (PMID 41174721, 2025).
prostate carcinoma (continued). "Moreover, the loss of primary cilia could hinder the synthesis of the Hh pathway repressor GLI3R, ultimately leading to aberrant activation of the androgen receptor in prostate cancer cells." (PMID 39785769, 2025). "Therefore, the key treatment strategy for advanced prostate cancer is to inhibit AR activity." (PMID 40163908, 2025). "These multifaceted changes result in a highly immunosuppressive TME that facilitates tumor growth, enables evasion of immune-mediated destruction, and may contribute to plasticity and resistance to therapies targeting the AR and other key pathways in prostate cancer." (PMID 41023204, 2025). "Therefore, AR has become an important target for the treatment of prostate cancer." (PMID 40224223, 2025). "VNPP433‐3β interrupts multiple signaling and metabolic pathways, including cholesterol biosynthesis, AR‐mediated transcription of several oncogenes, mRNA 5′ cap‐mediated oncogenic protein synthesis (by interrupting eIF4E‐Mnk1/2 signaling) and induces apoptosis in prostate cancer cells." (PMID 40007440, 2025). "Thus, GR could have both indirect and direct crosstalk relationships with E2F1 in NEPC, like the interaction between FOXA1 and GR in AR-positive prostate cancer cells." (PMID 39027480, 2024). "In addition to AR, other genetic factors contribute to ethnic disparities in prostate cancer." (PMID 39600743, 2024). "Similarly, NLRP3 acetylation and inhibition of inflammasome complex formation by androgen receptor inhibitor could block prostate cancer progression in nude-mice xenografts." (PMID 39769450, 2024). "In addition, the evaluation of this polymorphic locus of the AR gene allows us to reveal the CAG-polymorphic risk alleles for SBMA and prostate cancer in asymptomatic and affected patients, which is particularly relevant for patients with idiopathic non-obstructive azoospermia and oligozoospermia." (PMID 39596257, 2024). "Additionally, our Co-IP results further confirm FOXA1’s binding with AR in prostate cancer." (PMID 39097593, 2024). "Regarding the prostate cancer susceptibility‐related region, sourced from the DisGeNET database, there are 46% of AR peaks and 44% of H3K27ac peaks identified by CWAS located in, whereas RECWAS identified a higher proportion: 55% of AR peaks and 47% of H3K27ac peaks." (PMID 39099406, 2024). "Therefore, the role of Notch signaling may be context dependent in prostate cancer, with an oncogenic role in AR-driven disease and a tumor-suppressive role later in the context of lineage plasticity and conversion to NEPC." (PMID 39024561, 2024). "As the androgen receptor is essential for the growth and development of most prostate cancers and plays a key role in other cancers, the induction of AR-directed immunity via vaccination may offer an effective means to immunologically stimulate responses against these cancers." (PMID 39591176, 2024). "Notably, about half of the AR enhancers were co-occupied by p300 in prostate cancer cells, which was deterministic of stronger transcriptional activation evidenced both by higher accessibility and subsequent recruitment of the mediator and RNA polymerase II complexes." (PMID 38586029, 2024). "Importantly, the postulated inhibitor of BAG-1 isoforms, Thio-2, suppressed AR signaling and other important pathways implicated in the development and progression of CRPC to reduce the growth of treatment-resistant prostate cancer cell lines and patient-derived models." (PMID 38412481, 2024).
prostate carcinoma (continued). "Indeed, various studies in prostate cancer cell lines have shown that hydralazine restored the expression of silence genes and functioned synergistically with the androgen receptor antagonist enzalutamide and the histone deacetylases inhibitor (HDACi) panobinostat to exert anti-tumour effects." (PMID 39408757, 2024). "Thus, hnRNP K might have different phenotypic properties influencing the AR according to subsets of prostate cancer." (PMID 39000020, 2024). "Moreover, AR is critical for the development, progression, and treatment of prostate cancer (PCa)." (PMID 39529201, 2024). "Therefore, combinations with either GnRH agonists or with AR-targeting NHA is of specific interest for prostate cancer therapy and may also be considered in the future drug testing." (PMID 38783016, 2024). "Therefore, targeting oncogenic pathways other than AR signaling or their combined targeting could in principle be an effective therapeutic approach for treating metastatic or therapy-resistant prostate cancer." (PMID 38531859, 2024). "Importantly, from the DepMAP database, cumulative analysis of essentiality scores for all histone acetyltransferases (HATs) and histone deacetylases (HDACs) in AR-positive prostate cancer cell lines (namely VCaP and LNCaP) identified p300 as the most essential gene in these cell lines." (PMID 38586029, 2024). "Additionally, a recent study demonstrated that glucocorticoid treatment increased cell growth of AR-negative prostate cancer cells by altering the secretome of cancer-associated fibroblasts." (PMID 39027480, 2024). "To evaluate whether AZGP1 could affect microvessel density in AR + clinically localized human prostate cancer, we used the CellDIVE platform to perform multiplex immunohistochemistry analyses on a human prostate cancer tissue microarray (TMA) containing 215 cases." (PMID 38659028, 2024). "Moreover, it suggests that AR-targeted vaccines could be integrated into existing therapeutic regimens, potentially enhancing overall treatment efficacy for prostate cancer patients in a metastatic setting, as well as after an early diagnosis." (PMID 39591176, 2024). "Additionally, further investigation revealed that PAK6 could phosphorylate AR, leading to AR degradation and cell death in prostate cancer." (PMID 39233332, 2024). "Moreover, altered expression of several kinesins has been described to play a role in prostate cancer metastasis by promoting aberrant AR signalling and inhibiting apoptosis, but their role in regulating endosome-lysosome degradation dynamics remain relatively unexplored." (PMID 39796673, 2024). "Western blot analysis confirmed robust downregulation of direct targets (SMARCA2, SMARCA4, and PBRM1) and specific prostate cancer lineage proteins (AR, ERG, C-Myc, and PSA) after 5 d of AU-24118 treatment, whether administered alone or in combination with enzalutamide." (PMID 38557192, 2024). "Likewise, the AI treatment group significantly inhibited expression of hsd17b2 mRNA in ricefield eels, and it has been reported that overexpression of hsd17b2 in prostate cancer cell lines diminished androgen receptor signaling and suppressed androgen-induced cell proliferation." (PMID 39201749, 2024). "However, with prolonged treatment, there has revealed various molecular mechanisms leading to castration resistance in prostate cancer (CRPC), including aberrant overexpression of the AR gene, persistent activity of splice variants, and, notably, acquired somatic mutations." (PMID 38182647, 2024). "Especially, PSA expression in the prostate cancer cell line was sensitive to the pharmacological inhibition of both actin assembly and condensate formation, implicating a potential role for NM actin-dependent AR transcriptional activity in hormone-sensitive prostate cancer progression." (PMID 39000020, 2024).
prostate carcinoma (continued). "Finally, we tested the effect of UBX‐390 on AR mutants found in patients with treatment‐resistant prostate cancer to determine whether it could serve as a novel AR degrader with improved efficacy in treating therapy‐resistant prostate cancer." (PMID 38958553, 2024). "Taken together, these results demonstrate that menin suppresses metastasis in AR-negative prostate cancers, at least in part, by regulating a group of genes linked to metastatic pathways in a manner that is context-dependent and not solely dependent on AR status." (PMID 39336822, 2024). "Therefore, NM proteins might have some effects on AR expression or function in prostate cancer, and focusing on that aspect, we should evaluate the relation with NM proteins and AR in prostate cancer progression more deeply." (PMID 39000020, 2024). "In CWR22 AR‐positive prostate cancer cells, ENZ treatment strongly correlated with gene sets associated with OXPHOS, mitochondrial aerobic respiration, and respiratory electron transport chain, suggesting potential metabolic vulnerabilities that might influence ENZ sensitivity." (PMID 38859590, 2024). "There are more than 30 AR-Vs identified and AR-V7 is the most significant and well-characterized AR-V due to its proven role in prostate cancer, however, no studies have evaluated the association between AR-V7 and any other urogenital malignancy, including bladder cancer." (PMID 39083104, 2024). "Moreover, the human nucleoporins POM121 and importinβ mediate the nuclear import of a series of oncogenic transcription factors (e.g., such as the transcription factor E2F1 (E2F1), transcription factor p64 (c-Myc), and androgen receptor (AR), promoting the progression of prostate cancer (PCa)." (PMID 39080077, 2024). "Our findings indicate that epigenetic regulation is an important process, which may impact race-specific expression of genes associated with AR signaling in prostate cancer and adjacent non-tumor tissues." (PMID 38566104, 2024). "This study suggests that second-line treatment with an androgen receptor signaling inhibitor for castration-resistant prostate cancer after androgen receptor signaling inhibitors as first-line treatment may be more beneficial, particularly with abiraterone as the upfront treatment." (PMID 39135744, 2024). "Here, we evaluated the effect of androgen receptor (AR) inhibition by darolutamide in combination with DNA double-strand-break-inducing targeted radium-223 alpha therapy in vitro and in an intratibial LNCaP xenograft model mimicking prostate cancer metastasized to bone." (PMID 39769434, 2024). "For example, elucidating the androgen receptor (AR) structure and activity, along with its actions in cancer cell lines, led to rational drug design for treating prostate cancer, where drugs preventing androgen production and/or blocking AR action inhibit the growth of prostate cancer." (PMID 39459070, 2024). "As the treatment landscape for prostate cancer gradually evolves, the frequency of treatment-induced neuroendocrine prostate cancer (NEPC) and double-negative prostate cancer (DNPC) that is deficient for androgen receptor (AR) and neuroendocrine (NE) markers has increased." (PMID 38667288, 2024). "Indeed, prostate cancer chemotherapeutics such as docetaxel function by stabilising microtubules, leading to mitotic arrest and apoptosis of cancer cells, in addition to inhibiting translocation of the oncogenic androgen receptor (AR) to the nucleus." (PMID 39796673, 2024). "Menin may also promote AR-positive prostate cancer growth by promoting JunD and TMPRSS2 expression." (PMID 39336822, 2024). "In addition to AR, prostate cancer is classified based on the stage and the grade (Gleason score) that, along with histopathological and molecular features and patient characteristics, drive the appropriate clinical management of prostate cancer." (PMID 38937754, 2024).